MMP8 (matrix metallopeptidase 8)
Diseases named in the same sentence as MMP8 in open-access papers (continued):
Sharing a sentence is not in itself a finding about the gene and the disease.
periodontal disease (continued). "Tissue breakdown in periodontal disease can be detected through elevated salivary levels of matrix metalloproteinase-8 (MMP-8), while epigenetic alterations, such as hypermethylation in tumor suppressor genes like p16INK4a and MGMT, provide early warning signals for oral cancer." (PMID 41303669, 2025). "Active MMP-8 is strongly correlated with an increased severity of periodontal disease, from gingivitis > P-stage III > P-stage IV, and a higher diagnostic accuracy for periodontal disease than health." (PMID 40299548, 2025). "Furthermore, the strong correlation between MMP-8 and IL-1β underscores the relevance of these biomarkers in periodontal disease progression." (PMID 40362854, 2025). "According to the findings of this study, IL-1β and MMP-8, as salivary biomarkers, may be helpful in diagnosing periodontal disease." (PMID 40283051, 2025). "In children with periodontal disease, active MMP-8 is a potential tool for diagnosing periodontal inflammation, so in addition to measuring PD, a matrix metalloproteinase-8 test was performed from the saliva of the participants in the scientific work by Schmidt." (PMID 38254696, 2024). "Its activity is linked to periodontal disease progression, and its detection is valuable in diagnosing periodontal and inflammatory diseases, due to its specificity and role in tissue degradation, which total/latent MMP-8 (nowadays abbreviated by MMP-8) lacks." (PMID 39767238, 2024). "MMP-8 and MMP-9 have been linked to human periodontal disease, according to numerous research." (PMID 38535833, 2024). "An increase in the concentration of MMP-8 in saliva, a marker commonly used in humans for the identification of various illnesses, has been utilized to validate the emergence of particular kinds of periodontal disease." (PMID 38535833, 2024). "While MMP-8 is important for normal tissue remodeling and repair, excessive or uncontrolled production of this enzyme can lead to tissue destruction and the progression of periodontal diseases." (PMID 36900047, 2023). "Furthermore, aMMP-8 has been shown to be a more specific marker for active periodontal disease than total MMP-8, which can be found in both active and inactive forms." (PMID 36900047, 2023). "This study aims to investigate the impact of ADT on salivary MMP‐8 level and periodontal parameters, which might be useful in monitoring periodontal disease in prostate cancer patients undergoing ADT." (PMID 35769040, 2022). "As a result, MMP‐8 has been identified as a significant biomarker in periodontal disease." (PMID 35769040, 2022). "The panel of biochemical tests should be expanded to include CRP in saliva, and the concentration of IL-1β, OPG, RANKL and MMP-8 in the blood, which would allow for a discussion of the results in saliva in the context of the analyzed role of periodontal disease in the course of stroke." (PMID 35893412, 2022). "Measurement of MMP-8 can thus help manage periodontal diseases." (PMID 35330371, 2022). "MMP-8 is of great significance as it is involved in the progression of periodontal diseases." (PMID 35330371, 2022). "Various MMP‐8 measurement techniques with varying degrees of agreement may limit its applicability as an adjunctive tool for periodontal disease screening." (PMID 35769040, 2022). "Several studies found a linear relationship between MMP‐8 levels and periodontal disease severity." (PMID 35769040, 2022). "The pooled SMD indicated a statistically significant decrease in the GCF MMP-8 levels with probiotic supplementation compared to the controls in patients with periodontal disease (SMD = 0.819, 95% CI: 0.417, 1.221, I2 < 0.001, p-value ≤ 0.05, and n = two studies)." (PMID 35268009, 2022). "Furthermore, the contribution of MMP-8, from periodontal disease activity likely reduced the resolving power of caries profiles." (PMID 34575643, 2021). "The use of active and total MMP-8 could represent a useful adjunctive tool for the diagnosis and severity of periodontal disease." (PMID 34441437, 2021).
periodontal disease (continued). "MMP-8 is considered one of the main collagenases related to connective tissue and alveolar bone destruction and it is considered a crucial mediator of established irreversible periodontal disease." (PMID 34353321, 2021). "Also, MMP-8 can be used to predict the progression of periodontal disease or the response to periodontal therapy." (PMID 32503210, 2020). "A key characteristic of active periodontal diseases is the pathological elevation and activation of MMP-8 to active MMP-8 (aMMP-8) in periodontal tissues, which are reflected in oral fluids (e.g., saliva, mouth rinse, gingival crevicular fluid, and peri-implant sulcular fluid)." (PMID 30360358, 2018). "This variation in MMP-8 levels can serve as an indicator for periodontal disease development." (PMID 28074077, 2016). "Furuholm and co-authors suggested that increased salivary levels of MMP-8 could reflect periodontal disease activity in patients with coronary artery disease compared to systemically healthy controls." (PMID 26132583, 2015). "The acute myocardial infarction seems to influence the degree of periodontal inflammation, thus the measurement of the gingival crevicular fluid MMP8 levels seems to be a helpful biochemical test to obtain information about the severity of the periodontal disease." (PMID 21219642, 2011). "Thus, IL-1β and MMP-8 reflect distinct but complementary processes—early inflammation and structural destruction—highlighting their dual relevance for diagnosing and monitoring periodontal disease." (PMID 40283051, 2025). "MMP-8 is also necessary for defensive immune responses and tissue repair and remodeling, but its excessive degranulation by triggered neutrophils and concomitant activation in response to inflammation eventually lead to destruction and the progression of periodontal disease." (PMID 39273368, 2024). "Periodontal disease was successfully induced in rats using the ligature technique on the lower incisors, as confirmed by clinical parameters and the increase in salivary MMP-8 levels and plasma levels of IL-1 and TNF-α, regarded as biomarkers of periodontal disease." (PMID 36840029, 2023). "A limitation of our study pertains to the cross‐sectional study design, which could not infer a causal relationship between periodontal disease severity and the level of MMP‐8." (PMID 35769040, 2022). "Consequently, an increase in MMP‐8 levels is the result of periodontal disease." (PMID 35769040, 2022). "However, different MMP-8 measurement methods with different levels of agreement may limit its applicability as an adjunctive tool for periodontal disease screening." (PMID 34441437, 2021). "In general, active MMP-8 levels seem to be more accurate than total MMP-8 measurements in the screening of periodontal disease, and it could be recommended in oral fluids as a diagnostic biomarker for periodontal disease." (PMID 34441437, 2021). "Interleukin-1 beta (IL-1β) and matrix metalloproteinase-8 (MMP-8) are prominent salivary biomarkers that provide valuable insights into the detection and progression of periodontal disease." (PMID 40283051, 2025). "Matrix metalloproteinases, particularly MMP-8 and MMP-9, have gained significant attention as potential biomarkers for periodontal disease." (PMID 39275315, 2024). "Matrix metalloproteinase-8 (MMP-8), a collagenase, is recognized as a key biomarker used for predicting, diagnosing, prognosticating treatment, and classifying periodontal disease." (PMID 38940878, 2024). "The authors investigated the role of MMP-8, 9, IL-1β, IL-6, and TNF-α along with MIP-1α and found that MIP-1α had the highest discriminatory role in periodontal disease among adults." (PMID 38433948, 2024). "increased levels of matrix metalloproteinase-8 (MMP-8) in whole saliva and serum in patients with periodontal diseases and PCOS compared with healthy controls." (PMID 38021744, 2023).
periodontal disease (continued). "Among them, the concentrations of MMP-8 and MMP-9 increased significantly in patients with periodontal disease and those with advanced periodontal disease, which can be used as potential markers for periodontitis screening and diagnosis." (PMID 36769328, 2023). "Correlation with clinical parameters: Biomarkers such as IL-1β, MMP-8, and S100A8 are extensively researched in periodontal disease." (PMID 38192959, 2023). "The aim of this study is to further explore correlations between different MMP‐8 protein species in WB analysis and quantitative IFMA measurements, patient‐related factors, and periodontal disease surrogates." (PMID 37877535, 2023). "Especially fragmented low molecular size MMP‐8 species and PMN elastase activity are surrogates and biomarkers of periodontal disease activity and collagenolytic and proteolytic inflammatory burden." (PMID 37877535, 2023). "In this regard, recently, a novel prototype biosensor was developed and utilized to quantify salivary MMP‐8 using specific antibodies and surface acoustic wave (SAW) technology in patients with periodontal disease." (PMID 35304757, 2022). "Because type I collagen is the major component of the periodontal extracellular matrix, special attention has been paid to the role of collagenases, especially MMP-8 and MMP-13 and gelatinases, MMP-2 and MMP-9, in periodontal diseases." (PMID 35163727, 2022). "Moreover, according to recent systematic reviews and meta-analyses, salivary IL-1β, IL-6, and MMP-8 are among the five promising biomarkers that have been identified as eligible candidates for the diagnosis of periodontal diseases; while IL-10 may have a strong regulatory effect on immune responses." (PMID 35368315, 2022). "Various studies have shown that increased MMP-8 and MMP-9 levels characterize not only periodontal disease but also tend to increase during OTM." (PMID 33567492, 2021). "According to one study, AUC had the largest values for MMP-8, myeloperoxidase and MMP-9 in subjects with periodontal disease, the sensitivity to diagnosis being similar to the results obtained in the present study." (PMID 34829612, 2021). "Salivary IL-1β, MMP-8, ICTP, and Pg showed significant effectiveness for diagnosing periodontal disease." (PMID 34001101, 2021). "The levels and especially activation of MMP-8, MMP-9, and MMP-13 have been shown to be correlated with active stages of periodontal disease, and they decrease to levels found in periodontally healthy GCF after conventional periodontal treatment." (PMID 30669541, 2019). "Second, since the imbalance between MMP-8 and its inhibitor TIMP-1 is considered to initiate periodontal disease, we think that it would be much valuable to perform further analyses on both MMP-8 and TIMP-1 in the future." (PMID 29587716, 2018). "MMP-8 and MMP-9 are the most abundant MMPs in periodontal tissues reflecting periodontal disease severity, progression, and treatment response." (PMID 28218665, 2017). "Several MMPs have been detected in their different enzymatic forms in gingival tissue, gingival crevicular fluid (GFC), saliva, and mouth rinse, with MMP-8, MMP-13, and MMP-9 as the main proteases involved periodontal disease destruction." (PMID 28218665, 2017). "The objective of the current study was to investigate salivary MMP-8, -9, TIMP-1 and MPO levels in relation to MI and periodontal disease." (PMID 26132583, 2015). "The neutrophils are the major cells responsible for release of MMP and more importantly MMP-8 (collagenase-2) and MMP-9 (gelatinase-B) which is a concern to a periodontist as it is released during acute stages of periodontal disease." (PMID 24490073, 2013). "Moreover, by decreasing the salivary levels of MMP-8 and plasma levels of IL-1 and TNF-α, the biomaterial showed an immunomodulatory effect on the local and systemic biomarkers of the periodontal disease." (PMID 36840029, 2023).
periodontal disease (continued). "Also, C-reactive proteins (CRP), IL-12, MMP-8, MMP-9, and MMP-13 have been described as biomarkers for the periodontal disease." (PMID 35368315, 2022). "The exact mechanism of involving MMP-9 in intracellular signaling is unknown, but both MMP-8 and MMP-9 are markers of apical and periodontal disease." (PMID 32467797, 2020). "Salivary biochemical markers, which are characteristic for periodontal disease, include enzymes (MMP-1 (matrix metalloproteinase-1), MMP-8 (matrix metalloproteinase-8), MMP-9 (matrix metalloproteinase-9), immunoglobulins, and a group of proteins (albumin, fibronectin)." (PMID 32598403, 2020). "However, in the 11 studies included in this study, IL-1β, MMP-8 and TNF-α in saliva were the most frequently observed biomarkers in periodontal disease patients compared to healthy controls." (PMID 33383828, 2020). "By testing the MMP-8 and TIMP-1 levels and the MMP-8/TIMP-1 ratio, individuals with periodontal disease may be differentiated from subject in the control group." (PMID 31781639, 2019). "In addition to the biomarkers assessed, the inclusion of other parameters such as MMP-8, IL-1β, and TNF-α could provide comprehensive insights into the pathogenesis of periodontal disease." (PMID 41300847, 2025). "Extracellular metalloproteinases (MMPs), especially 8 and 9 (MMP-8 and MMP-9), play a major role in periodontal destruction, being observed at significantly higher levels in the gingival crevicular fluid (GCF) of patients with periodontal disease compared to healthy individuals." (PMID 41440322, 2025). "In addition, significant associations were found between MMP-8 and MMP-9 activities in gingival crevicular fluid and the severity of the periodontal disease, together with negative correlations with TIMP-1 and TIMP-2 levels." (PMID 37371608, 2023). "In contrast, in the present study, we determined whether or not individuals have periodontal disease using the ELISA technique, which assessed the total MMP‐8." (PMID 35769040, 2022). "In this study, the ROC curve demonstrated that the level of salivary MMP‐8 could distinguish between individuals with and without periodontal disease with an AUC value of about 0.8." (PMID 35769040, 2022). "However, their major contribution to the prediction of caries was not to be expected, as the proteases MMP-8 and MMP-9 are part of a highly complex “protease web”, which is mainly associated with destructive periodontal disease." (PMID 33806927, 2021). "The amount of IL-1, IL-8, MMP-8, MMP-9, and MMP-13 in saliva samples from patients with periodontal disease and healthy controls have been analyzed and compared, and one study compared hemoglobin levels in blood samples with biomarkers in saliva samples from patients with periodontal disease." (PMID 34199256, 2021). "However, other authors did not found differences in MMP-1 and MMP-8 expression in periodontal tissue and gingival crevicular fluid of diabetic and nondiabetic patients, both with periodontal disease." (PMID 22611374, 2012). "In our study the AMI patients showed higher MMP-8 levels, which might represent, together with the present periodontal disease, a further negative influence on the progression or severity of the myocardial infarction." (PMID 21219642, 2011). "In contrast to other studies that found higher levels of MMP-8 in patients with metal restorations and concomitant generalized periodontitis, we had no patients with active periodontal disease, as this could result in possibly higher aMMP-8 levels at the natural tooth site." (PMID 39941195, 2025). "Although the changes in salivary IL-1β and MMP-8 levels after non-surgical periodontal therapy were not significant, salivary cytokines could be used to confirm the effect of periodontal therapy or diagnose periodontal disease." (PMID 33383828, 2020). "The ROC curves for MMP-8 and MMP-9 indicated they were not significant periodontal disease biomarkers (p = 0.921 and p = 0.89, respectively)." (PMID 35562715, 2022).
periodontal disease (continued). "Negative correlations were shown between periodontal disease severity and GCF TIMP-1 and -2 levels, together with a positive correlation to MMP-8 and -9 activities." (PMID 33143325, 2020).